CD47 (CD47 molecule)
Diseases named in the same sentence as CD47 in open-access papers (continued):
Sharing a sentence is not in itself a finding about the gene and the disease.
cancer (continued). "The CD47 expression on inhibitory T cells might inhibit macrophage-mediated elimination in a manner that bears a superficial resemblance to the inhibition of macrophages by CD47+ cancer cells." (PMID 38216635, 2024). "Although CD47 is mainly upregulated by cancer cells, it is also expressed on many normal cells." (PMID 39767726, 2024). "CD47 is ubiquitously expressed on all cells, including cancer cells." (PMID 37066426, 2024). "SIRPα recognizes the ligand CD47, which is often overexpressed in cancer cells." (PMID 40458305, 2024). "Additional studies are needed to determine whether CRACD and other targets of IFT57 identified here contribute to the correlations between CD47 mRNA expression and survival in various cancers." (PMID 39201643, 2024). "However, data from recent clinical trials have called into question the use of anti-CD47 antibodies for the treatment of adult and pediatric cancers." (PMID 38920727, 2024). "Magrolimab is designed to block CD47 and help the immune system destroy cancer cells." (PMID 39702544, 2024). "This approach may overlook the crucial role of the CD47/TSP-1 axis in the anti-cancer immune response." (PMID 39138571, 2024). "Consequently, CD47-targeted DDS formulations can be employed not only in anti-cancer therapy but also in the treatment of atherosclerosis." (PMID 39201377, 2024). "Some cancer cells express CD47 protein and can evade macrophage phagocytosis." (PMID 39594611, 2024). "The targeting of CD47 is an immunotherapy strategy for the treatment of human cancer." (PMID 38832992, 2024). "However, the molecular mediators and mechanisms regulating the expression of CD47 by cancer cells and SIRPα by macrophages remain poorly defined." (PMID 38183060, 2024). "Many cancer cells exploit this mechanism and overexpress CD47." (PMID 38493445, 2024). "Our findings suggested that the small molecule compound SMC18, which dual-targets the CD47/SIRPα and PD-1/PD-L1 pathways, could be a candidate for promoting macrophage- and T-cell-mediated phagocytosis and immune responses in cancer immunotherapy." (PMID 38462636, 2024). "To date, many efforts have been made to block CD47/Sirpα to promote cancer cell phagocytosis." (PMID 38832992, 2024). "Therefore, the expression of CD47 needs to be researched in various malignant tumors in relation to treatment." (PMID 39795582, 2024). "The prognostic relevance of CD47 expression has been described in a number of cancer types." (PMID 38493445, 2024). "Combining TKIs with a CD47 blockade may offer therapeutic benefits in ALK+ cancers, especially in overcoming off-target resistance where TKIs alone are less effective." (PMID 39767726, 2024). "Additionally, the researchers found that cancer cells that became drug-resistant also became more vulnerable to macrophage-mediated cytotoxicity in response to anti-CD47 therapy." (PMID 38261139, 2024). "Thus, targeting the interaction between CD47 and its SIRPα receptor has emerged as a potential therapeutic strategy for cancer treatment." (PMID 39039207, 2024). "Its role in maintaining immune homeostasis makes CD47 an important target for cancer therapy." (PMID 38638433, 2024). "Consequently, the APHP‐CCCA‐induced shift from M2 to M1 macrophages, coupled with CD47 blockade, facilitated the phagocytosis of cancer cells, thereby activating the innate immune response." (PMID 39467056, 2024). "Therefore, the development of safe strategies that effectively disrupt the CD47-SIRPα signaling holds great potential for cancer treatment." (PMID 38405432, 2024). "CD47 plays an important role in cancer biology, immunology, angiogenesis, and tissue regeneration." (PMID 38562718, 2024). "All of these findings point to CD47 could be an early biomarker for cancer detection, staging, and monitoring." (PMID 38720108, 2024). "CD47 expression was shown in multiple cancer types, including LMS." (PMID 38473300, 2024).
cancer (continued). "CD47, an immune checkpoint protein overexpressed on various cancer cells, binds to Signal Regulatory Protein alpha (SIRPα) on macrophages to deliver "don't eat me" signal that prevents phagocytosis of cancer cells." (PMID 38462636, 2024). "In a therapeutic context, anti-CD47 mAb may inhibit CD47 DEMs, thus inducing phagocytosis of cancer cells expressing pro-phagocytic molecules." (PMID 39767726, 2024). "Conversely, IFT57 was also the top co-expressed gene with CD47 in several carcinomas." (PMID 39201643, 2024). "CD47 is a cell surface molecule that is widely expressed in most cancers." (PMID 37138855, 2023). "CD47+ is a protein expressed on the surface of cancer cells." (PMID 37808190, 2023). "One potential strategy to further overcome resistance to myeloid signaling may be therapeutic blockade of SIRPα-CD47, an emerging checkpoint utilized by cancer cells to evade immune responses." (PMID 37790486, 2023). "For example, it was found Hu5F9-G4, an anti-CD47 antibody, could inhibit the interaction of CD47 with SIRPα and promoted macrophage-mediated phagocytosis to kill cancer cells." (PMID 36816959, 2023). "Subsequently, we speculated that MφNPs with SIRPα on their surface could disrupt the SIRPα-CD47 interaction between macrophages and cancer cells, hence activating macrophage phagocytic capacity." (PMID 38111068, 2023). "Furthermore, authors documented a substantial positive connection between high CD47 expression and poor prognosis for cancer, leading to several approaches aimed at blockade of this signaling axis." (PMID 38033495, 2023). "Together, these data demonstrate that the armed MyxV could infect cancer cells and express similar levels of CD47 and IFN-γ as compared to those in single armed viruses." (PMID 37835397, 2023). "Despite current work targeting CD47 and PD‐L1 checkpoints, the Fus‐CV platform could be extended to simultaneously target other checkpoints to synergize cancer immunotherapy." (PMID 37409429, 2023). "Many cancers with poor prognosis express CD47 at high levels compared to normal cells." (PMID 36937769, 2023). "During the development of cancer, cancer cells developed complex mechanisms to escape the attack from the body's immune system, which plays an important role in immune escape through overexpression of CD47 molecules." (PMID 37128288, 2023). "Furthermore, CD47 expression appeared to be more consistent across different cancer cell lines than Siglec-9 Fc binding." (PMID 37444515, 2023). "However, little is known about the genetic and epigenetic regulation of the expression of CD47 in cancer cells." (PMID 36413402, 2023). "Therefore, we can assume that they had antitumor activity and responded against cancer cells; however, more studies are needed to confirm this, including CD47 expression in cancer cells, as a surface protein that interacts with monocytes." (PMID 36674504, 2023). "CD47 is expressed at high levels in various types of cancer cells compared to normal cells." (PMID 36768216, 2023). "Cancer cells express CD47 on the cell surface to avoid phagocytosis by macrophages." (PMID 36768216, 2023). "CD47 is a transmembrane protein of the immunoglobulin (Ig) superfamily and is overexpressed in several cancers, which could directly bind with SIRPα to deliver the “don’t eat me” signal that exerts anti-phagocytosis function." (PMID 37334368, 2023). "CD47 is expressed at a low level in normal cells and upregulated in most of cancer cells." (PMID 36419386, 2023). "Our study reveals that RAGA serves as the upstream promoting regulator of CD47 degradation and may represent a biomarker for cancer diagnosis." (PMID 36823443, 2023). "However, other evidence revealed that cancer immunotherapy targeting CD47 can induce cancer cells to leak mtDNA into nearby dendritic cells and present antigens to effector T cells, bridging the innate and adaptive immune systems." (PMID 37525297, 2023).
cancer (continued). "In addition to known factors such as CD47, they have identified many ADCP sensitive regulators in cancer cells, including adipocyte plasma membrane associated protein (APMAP) enzymes which was poorly characterized." (PMID 37427373, 2023). "Thus, blocking CD47 signaling is a promising immunotherapeutic strategy for diverse cancer cell types." (PMID 37189735, 2023). "Targeting CD47–SIRPα can eliminate cancer cells through multiple mechanisms." (PMID 37894750, 2023). "Indeed, the blocking antibody against SIRPα on macrophages favors the phagocytosis of CD47-expressing cancer cells." (PMID 36829496, 2023). "Consequently, the CD47–SIRPα protein complex has been recognized as a potential therapeutic target in cancer and inflammation." (PMID 37999357, 2023). "However, the red blood cell (RBC) toxicity is the big concern for the development of CD47-based anti-cancer therapeutics." (PMID 36593962, 2023). "Related studies suggested that miRNA-133a may be involved in downregulating CD47 in human HeLa cancer cells." (PMID 37697243, 2023). "The protein level of CD47 was higher in A549, H1299 cancer cells than in HBE normal cells." (PMID 36823443, 2023). "Moreover, cancer cells can overexpress antiphagocytic molecules such as CD47, ultimately inhibiting the inflammatory response and facilitating immune escape of cancer cells." (PMID 36768820, 2023). "Other cancer treatment strategies are looking at CD47 as a potential therapeutic target." (PMID 36937769, 2023). "Whereas the forward action of CD47-SIRPα is to repel phagocytosis initiated by macrophages, we speculated that the reverse signaling supports pro-survival activities of the entrapped cancer cells." (PMID 37848444, 2023). "However, the mechanism of CD47 expression in cancer tissues is complex and appears to go beyond simply a “don’t eat me” signal." (PMID 37373873, 2023). "Our simulation results thus extend the present understanding of cooperative effects in CD47–SIRPα interactions and may have an influence on the advancement of new cancer treatments." (PMID 37999357, 2023). "Besides CD47, other proteins that help in cancer cell self‐recognition and tumor self‐targeting are focal adhesion proteins, focal adhesion kinase, and RHO family proteins." (PMID 36925703, 2023). "CD47-SIRPA pair was observed between cancer cells and TAMs in our analysis." (PMID 37945567, 2023). "Since cell-surface expression of CD47 is a major mechanism used by cancer cells to evade macrophage phagocytosis, we investigated whether the KRAS mutation status could affect CD47 expression in lung tumors." (PMID 36413402, 2023). "All these information supports the development of CD47-based therapies for cancer treatment." (PMID 36593962, 2023). "Accumulating evidence suggests that ICB of CD47 is a promising novel way to cure cancer." (PMID 37063284, 2023). "One such checkpoint, CD47, is a transmembrane protein overexpressed on the membrane of cancer cells that binds to signal-regulatory protein alpha (SIRPα) of innate immune cells, sending a “don’t eat me” signal and helping the escape of cancer cells from the immune system." (PMID 37759771, 2023). "Furthermore, both PDAC subtypes expressed similar levels of Cd47, a contact-dependent anti-phagocytotic signal often upregulated by cancer cells to escape elimination by phagocytes." (PMID 37156840, 2023). "Interestingly, as an antiphagocytic molecule, CD47 also exhibited very high expression in cancer cells." (PMID 36529697, 2023). "Localization of CD47 on the cancer cell surface is essential for preventing phagocytic clearance." (PMID 36823443, 2023). "More recent exploration of the cancer engulfment hypothesis has uncovered additional pathways including calreticulin, CD22, and CD24 that intersect with or run parallel to the SIRPα-CD47 pathway and are also potential targets in cancer." (PMID 36459066, 2023).
cancer (continued). "Blocking the CD47-SIRPα signaling axis and promoting repolarization from M2 to M1 in the tumor microenvironment can significantly prevent the local recurrence and distant metastasis of malignant tumors." (PMID 37808190, 2023). "Interestingly, our study indicates that FOXP3 has the strongest association with CD47, and infiltration of FOXP3 cells is correlated with poor prognosis in several cancers." (PMID 36598153, 2023). "Finally, we found that the expression of STC1, AKR1B1, and CD47 was increased along cancer invasion in clinical CRC samples using immunohistochemical staining." (PMID 36816947, 2023). "The dual effects make CD47 a promising therapeutic target for cancer immunotherapy." (PMID 38188674, 2023). "Indeed, blocking CD47-SIRPα interaction via anti-CD47 antibodies restored cancer cell phagocytosis and destruction by macrophages." (PMID 36882648, 2023). "Inhibiting the interaction between cancer cells and macrophages and inducing phagocytosis may be achieved by CD47-blocking drugs, such as monoclonal antibodies that target CD47/SIRPα." (PMID 37569598, 2023). "Cancer cells overexpress CD47, which is involved in the SIRPα-CD47 pathway, on their surface." (PMID 36797756, 2023). "Therefore, immune checkpoint inhibitors that block the CD47/SIRPα pathway have been developed and applied in cancer therapy." (PMID 37049910, 2023). "Furthermore, CD47 expressed on cancer cells and stromal cells can also interact with SIRPα on MDSCs and inhibit their activation and differentiation into mature macrophages and DCs." (PMID 38188674, 2023). "Although some trials have confirmed CD47 saturation on cells in circulation following antibody administration, confirmation of antibody binding to cancer cells sampled from on-treatment biopsies would be required to confirm this hypothesis." (PMID 37958404, 2023). "Furthermore, in vivo mouse model results revealed that IMM0306 exerts excellent cancer killing efficacy by activating both macrophages and NK cells via blockade of CD47-SIRPα interaction and FcɣR engagement." (PMID 36575242, 2023). "Besides the CD47-SIRPα axis, other immune checkpoints, such as Siglec receptors, are also vital targets for cancer immunotherapy." (PMID 38008741, 2023). "Our laboratory recently demonstrated that the ERM family post-translationally modulates the cellular surface localization of PD-L1, which belongs to a group of IgG superfamilies similar to CD47, by serving as a scaffold protein in several cancer cell types, including PDAC." (PMID 37189735, 2023). "The interaction between CD47 on cancer cells and signal regulatory protein alpha (SIRPα) on myeloid cells transmits a signal that prevents the cancer cells from immune detection and phagocytosis, allowing them to evade immune clearance and proliferate unchecked." (PMID 38188674, 2023). "However, only cancer cells also expressed pro-phagocytic signals, so that after blocking CD47, the “eat me signals” were activated only in cancer cells." (PMID 37371818, 2023). "Therefore, a neutralizing antibody against CD47 or an inhibitory antibody against SIRP-α (a CD47 recognition receptor expressed on macrophages) has been reported to increase the phagocytic activity of macrophages against cancer cells." (PMID 36768216, 2023). "Also, the interaction of SIRPα on macrophages and CD47 on cancer cells inhibits the clearance of cancer cells via phagocytosis." (PMID 38111068, 2023). "CD47-SIRPα plays an important role in regulating the immune system, and CD47 can bind to the SIRPα protein on the surface of immune cells to inhibit immune cells from phagocytosing cancer cells." (PMID 37731525, 2023). "Meanwhile, CD47 as an immunoglobulin family member protein overexpressed in various cancers." (PMID 37171006, 2023). "Furthermore, we demonstrated that patients with high CD47 expression showed a poor prognosis, indicating that cancer cells in GCLM escape phagocytosis by increasing CD47 expression." (PMID 36860925, 2023).
cancer (continued). "Furthermore, targeting of this cross-talk has emerged as a promising strategy for cancer treatment with the antibody against CD47 protein, a critical macrophage checkpoint recognized as the “don’t eat me” signal, as well as other metabolism-focused strategies." (PMID 38033495, 2023). "Cancer cells may also overexpress CD47, providing a ‘don’t eat me’ signal to escape macrophage attention." (PMID 37232754, 2023). "One of these signals is CD47, which is overexpressed in many cancers." (PMID 37143666, 2023). "An enhanced understanding the role of CD47 as a biomarker may pave the way for developing personalized therapeutic approaches targeting CD47 in cancer patients." (PMID 38188674, 2023). "Through the overexpression of anti-phagocytic surface proteins, also known as the “don’t eat me” signal, such as CD47, programmed cell death ligand 1 (PD-L1), and the beta-2 microglobulin subunit of the major histocompatibility class I complex (B2M), cancer cells can evade clearance by macrophages." (PMID 37846296, 2023). "Therefore, it was necessary to block the connection between them using ICIs - CD24 and CD47 antibodies, enabling macrophages to begin phagocytosing cancer cells more effectively." (PMID 37875918, 2023). "Notably, CD47-targeted therapies offer a promising avenue for improving cancer treatment outcomes, especially when combined with other immunotherapeutic approaches." (PMID 38188674, 2023). "This may be beneficial to efficiently target the CD47-SIRPα phagocytosis inhibitory signal in cancer immunotherapy research." (PMID 36813842, 2023). "Moreover, preclinical studies have revealed that blocking CD47 inhibits solid tumor growth and enhances the efficacy of conventional chemotherapy, radiation therapy, and some targeted cancer therapies 13-15." (PMID 36860925, 2023). "The CD47 protein (also known as integrin-associated protein, IAP) is a transmembrane protein expressed on both healthy and cancer cells, transducing a ‘don’t eat me’ signal when it binds to the SIRPα receptor expressed on myeloid cells to negatively regulate phagocytosis." (PMID 37691932, 2023). "Since the SIRPα–CD47 protein complex has been recognized as a promising therapeutic target in cancer, our detailed studies on the cooperative binding of CD47 to SIRPα may have an influence on the advancement of new cancer treatments." (PMID 37999357, 2023). "CD47 is a promising and highly anticipated novel target for checkpoint-inhibitor blockade in which early trials are showing significant efficacy in anti-cancer activity." (PMID 37920162, 2023). "Opsonizing cancer cells with antibodies targeting specific proteins upregulated in tumors tags them for clearance by the complement system, phagocytes, and/or NK cells, rationalizing combinations of therapeutic antibodies with CD47 blockade." (PMID 37958404, 2023). "However, cancer cells often overexpress CD47, a “don’t eat me” signal that helps cancer cells evade TAM-mediated phagocytosis by interacting with its receptor SIRPα on TAMs." (PMID 36594466, 2023). "Targeting CD47-mediated signaling may represent a promising strategy for cancer immunotherapy by disrupting the communication between cancer cells and stromal cells in the TME." (PMID 38188674, 2023). "Second, a CD47 SNP that has been reported to be associated with other cancers was selected, and other SNPs were not investigated." (PMID 37545625, 2023). "Importantly, CD47‐SIRPα blockade with an anti‐CD47 antibody treatment significantly enhances EGFR‐targeted cancer therapy." (PMID 37541303, 2023). "One challenge is that CD47 is not only expressed on cancer cells but also on healthy cells, which may lead to unintended effects of therapy." (PMID 38188674, 2023). "Furthermore, THC formation in co-culture was increased by pre-blocking CD47-SIRPα signals in cancer cells with an antibody." (PMID 37848444, 2023).